NAT1 (N-acetyltransferase 1)
Diseases named in the same sentence as NAT1 in open-access papers (continued):
Sharing a sentence is not in itself a finding about the gene and the disease.
breast carcinoma (continued). "NAT1 has been included in signatures for breast cancer identification and staging, as a prognostic marker in male breast cancer and non-triple negative breast cancer." (PMID 29969986, 2018). "NAT1 expression in breast cancer was examined by Probit analysis using data from METABRIC (n = 1980)." (PMID 29969986, 2018). "NAT1 is included in the Prosigna Breast Cancer Prognostic Gene Signature Assay (PAM50), which has proven to be useful in identifying patients most likely to benefit from drug treatment." (PMID 29969986, 2018). "NAT1 mRNA can be used to segregate breast cancer patients into sub-populations that demonstrate different overall survival." (PMID 29969986, 2018). "There have been a number of other studies that have reported the effects of NAT1 in breast cancer recurrence and overall survival." (PMID 29969986, 2018). "The NAT1 transcript is a potential target for mir-1290, which is differentially expressed in breast cancer." (PMID 29969986, 2018). "The higher levels of NAT1 in luminal versus basal breast cancer suggests a relationship with ER expression." (PMID 29969986, 2018). "Human NAT1 expression in breast cancer is predicted to be a valuable indicator for antiestrogen responsiveness and an indicator of a positive prognosis, particularly in ER+ breast cancer." (PMID 28359264, 2017). "A novel role for rat NAT2 in mammary cancer was discovered unrelated to carcinogen metabolism, suggesting a role for human NAT1 in breast cancer." (PMID 28359264, 2017). "Recent investigations suggest role(s) of human arylamine N-acetyltransferase 1 (NAT1) in breast cancer." (PMID 28359264, 2017). "The results reported in the current study suggest that the human NAT1 (an ortholog of rat NAT2) phenotype and prepubescent carcinogen exposure should be studied as additional factors in human breast cancer susceptibility." (PMID 28359264, 2017). "Several microarray studies have shown that elevated NAT1 expression is correlated with estrogen receptor positive (ER+) breast cancer samples." (PMID 28359264, 2017). "Here, we have investigated the role of NAT1 in the invasiveness of breast cancer cells both in vitro and in vivo." (PMID 25627111, 2015). "We showed that NAT1 protein expression was a prognostic marker in breast cancer patients, which supports previous reports by other groups." (PMID 25528056, 2014). "The small molecule inhibitor Rhod-o-hp was used to investigate the effect of NAT1 inhibition in MDA-MB-231 breast cancer cells." (PMID 25528056, 2014). "We next analyzed the correlation between the presence of NAT1 protein in breast cancer tissues and patient prognosis." (PMID 25528056, 2014). "The expression levels of NAT1 protein in breast cancer tissues was examined by immunohistochemistry (IHC)." (PMID 25528056, 2014). "Regarding breast cancer, several independent studies showed that NAT1 expression clustered with expression of the estrogen receptor." (PMID 25528056, 2014). "Breast cancer tissues are reported to exhibit lower promoter methylation rates than normal breast, and DNA hypomethylation of the NAT1 gene plays a significant role in breast carcinogenesis." (PMID 23819905, 2013). "Human arylamine N-acetyltransferase 1 (hNAT1) has become an attractive potential biomarker for estrogen-receptor-positive breast cancers." (PMID 23940600, 2013). "Recently, small molecular inhibitors of NAT1 have been successful in inhibiting proliferation and invasiveness of breast cancer cells in culture." (PMID 23819905, 2013). "Among the other genes in the list, NAT1, DNALI1, SCUBE2, and TFF1 have been implicated in breast cancer." (PMID 23365541, 2012). "In human breast cancer samples, NAT1 mRNA levels have been shown to cluster with a group of genes that included the estrogen receptor, being highest in luminal-type carcinomas and lowest in basal-like carcinomas." (PMID 21347396, 2011).
breast carcinoma (continued). "Both regression and Bayes Model Averaging highlighted a significant effect of NAT1*10 on breast cancer, while regression analysis also suggested a significant effect for packyears and for the interaction of packyears and NAT2." (PMID 21080951, 2010). "It appears that human NAT1 is a marker for oestrogen receptor positive breast cancer, although information is still accumulating on the relationship of this marker to others, including the oestrogen receptor itself." (PMID 18280460, 2008). "Several studies highlighted the role of XME gene polymorphisms such as CYP1A1, CYP1B1, CYP2D6, mEH, GSTT1, GSTM1 and NAT1 in treatment efficacy as well as survival after treatment of breast carcinoma." (PMID 18423013, 2008). "A correlation between human NAT1 overexpression and oestrogen receptor status in breast cancer tissues has been described which implicates human NAT1 in oestrogen-positive breast tumours and in relapse-free survival prognosis." (PMID 17896208, 2008). "There is also evidence that the level of expression of human NAT1 affects the growth of cultured breast cancer cells." (PMID 18280460, 2008). "There is increasing evidence that human arylamine N-acetyltransferase type 1 (NAT1, EC 2.3.1.5), although first identified as a homologue of a drug-metabolising enzyme, appears to be a marker in human oestrogen receptor positive breast cancer." (PMID 18280460, 2008). "Both studies reported that NAT1 knockout in breast cancer cells increased glycolytic activity." (PMID 37107601, 2023). "However, the exact molecular and cellular importance of NAT1 expression in breast cancer remains elusive." (PMID 37107601, 2023). "Based on the data presented here and the current literature on NAT1 KO in breast cancer cells, we believe that mitochondrial function is reduced by NAT1 KO and further that the fate of glucose is altered, resulting in less glucose flux through the TCA/Krebs cycle." (PMID 37107601, 2023). "MicroRNA-6744-5p facilitated anoikis and targeted NAT1 in breast cancer cells." (PMID 37350934, 2023). "Additionally, other various reports suggested that the inhibition of NAT1 using small molecule and siRNA silencing, showed reduced invasiveness and proliferation of breast cancer cells." (PMID 37469704, 2023). "Recent studies found that arylamine N-acetyltransferase 1 (NAT1) is frequently upregulated in breast cancer, further suggesting NAT1 could be a potential therapeutic target for breast cancer." (PMID 37107601, 2023). "Lastly, the data presented here are important, as they provide further evidence that NAT1 knockout in breast cancer cells results in an altered metabolomic profile and provides additional evidence that NAT1 is related to proper mitochondrial functions in breast cancer cells." (PMID 37107601, 2023). "Notably, the transcripts occupying the block associated with PAM50 subtype include CA12, GABRP, NAT1 and TBC1D9, which have been previously proposed as predictor genes for breast cancer mortality, recurrence and drug response." (PMID 35758795, 2022). "Furthermore, understanding of NAT1 regulation in breast cancer can be potentially applied to development of new therapies using small molecules like the ones presented here." (PMID 35153780, 2022). "Furthermore, NAT1 overexpression in primary breast cancer tumors is higher in ER+ compared to ER− primary tumors." (PMID 35153780, 2022). "Approximately, 30% of tumours from breast cancer patients have undetectable levels of NAT1 mRNA." (PMID 35918499, 2022). "The role of NAT1 in breast cancer, until recently, was thought to center on NAT1’s ability to metabolize/activate carcinogens, however it has been shown that rats with higher Nat2 expression (orthologous to human NAT1) had greater mammary tumor susceptibility, independent of carcinogen metabolism." (PMID 35046826, 2021). "Despite numerous studies investigating NAT1 in breast cancer, the exact effect of increased NAT1 expression in breast cancer remains unknown." (PMID 35046826, 2021).
breast carcinoma (continued). "Additionally, our recent work examining differences in the metabolome between breast cancer cell lines expressing varying levels of NAT1 suggested a role for NAT1 in the metabolism of l-asparagine, putrescine, and l-lysine." (PMID 35046826, 2021). "Moreover, the genetic or pharmacological inhibition of NAT1 retards anchorage-independent cell growth in breast cancer." (PMID 33435156, 2021). "Human arylamine N-acetyltransferase 1 (NAT1) has been extensively studied in breast cancer." (PMID 35046826, 2021). "However, the molecular and cellular effects of NAT1 expression in breast cancer remain to be completely understood." (PMID 31910058, 2020). "These metabolites have recently been implicated in enhanced cell growth and metastatic potential in breast cancer models suggesting they may be the key to understanding how varying levels of NAT1 affect breast cancer progression." (PMID 32555504, 2020). "Previous studies have demonstrated that XBP1 expression is correlated with NAT1 expression, and XBP1 and NAT1 may share a common transcriptional network in breast cancer." (PMID 32793479, 2020). "The objective of this study was to evaluate the effect of varying levels of NAT1 N-acetylation activity in MDA-MB-231 breast cancer cells on global cellular metabolism and to probe for unknown endogenous NAT1 substrates." (PMID 32555504, 2020). "Based on this finding, targeting and inhibiting NAT1 expression or activity may increase the sensitivity of breast cancer to chemotherapeutic agents." (PMID 32555504, 2020). "According to Egeberg and collaborators, with respect to slow acetylators, the incidence ratio of breast cancer among those carrying the fast NAT1 genotype was 1.43 (95% CI 1.03–1.99) and among those with the intermediate/fast NAT2 allele, risk was 1.13 (95% CI 0.83–1.54)." (PMID 32085420, 2020). "Beyond pharmacogenetics, NAT1 is also relevant to breast cancer." (PMID 31358821, 2019). "Although the effects of NAT1 KO on cell-doubling time were inconsistent across the three breast cancer cell lines, the ability of the NAT1 KO cell lines to form anchorage-independent colonies in soft agar was dramatically and consistently reduced in each of the breast cancer cell lines." (PMID 31531019, 2019). "Moreover, metastatic disease retains the level of NAT1 expression seen in primary tumors, at least for breast cancers." (PMID 29518119, 2018). "There are multiple populations in breast cancer that can be segregated based on NAT1 mRNA levels." (PMID 29969986, 2018). "Our results in Nat2 congenic rats suggest that human genetic variation resulting in differential NAT1 activity may influence human breast cancer." (PMID 28359264, 2017). "We first examined the effect of inhibiting NAT1 in breast cancer cell lines." (PMID 25627111, 2015). "Deciphering exactly how NAT1 may influence the expression of N-cadherin and/or β-catenin will be pivotal to understanding its effects on breast cancer cell morphology." (PMID 25627111, 2015). "In summary, the present study demonstrates a role for NAT1 in breast cancer metastasis that may be independent to its role in arylamine metabolism." (PMID 25627111, 2015). "Furthermore, in a study of primary male breast cancers, NAT1 positivity was reported to be correlated with better outcome." (PMID 25528056, 2014). "The aim of the present study was to determine whether NAT1 is a bona fide target of miR-1290, and to investigate the impact of NAT1 on breast cancer prognosis." (PMID 25528056, 2014). "The aim of the present study was to clarify whether NAT1 is a bona fide target of miR-1290 and to investigate the impact of NAT1 expression on breast cancer prognosis." (PMID 25528056, 2014). "Bièche at al (2004) provide evidence that NAT1 may be an ERα-responsive gene in human breast cancer." (PMID 19352457, 2009).
breast carcinoma (continued). "However, if the human NAT1 enzyme is to be considered as a target for breast cancer therapy, it is essential that there is a suitable in vivo animal model for testing." (PMID 18280460, 2008). "In view of the relationship between the expression of human NAT1 and oestrogen receptor positivity in breast cancer, we wished to investigate the effects of steroidogenic compounds and xenobiotic oestrogenic compounds, including tamoxifen, on the activity of mouse Nat2." (PMID 18280460, 2008). "The possibility that human NAT1 may serve as a marker for sub-dividing populations of different breast cancers is intriguing." (PMID 18280460, 2008). "However, this hypothesis requires additional studies involving more mechanistic in vitro and in vivo models using NAT1 knockout and cytotoxic nucleosides concomitantly for breast cancer treatments." (PMID 37107601, 2023). "Moreover, NAT1 is required for invasion in a mouse model of breast cancer pulmonary metastases suggesting it may be a druggable target in some cancers." (PMID 31910058, 2020). "In a follow-up study, they also demonstrated a high correlation between positive immunostaining for NAT1 and expression of EMT signature genes in breast cancer, suggesting that increased NAT1 expression may contribute to the EMT of breast cancers and subsequently their metastatic potential." (PMID 31531019, 2019). "Importantly, NAT1 knockdown in MDA-MB-231 cells resulted in a significant reduction in their ability to metastasize to and colonize in the lungs when injected into nude mice, suggesting that increased NAT1 level in breast cancer cells can contribute to their metastatic properties in vivo." (PMID 31531019, 2019). "The KO of NAT1 activity by both gRNA #2 and gRNA #5 in MDA-MB-231 breast cancer cells caused a modest but significant (p < 0.0001) elevation in doubling time but neither gRNA #2 or gRNA #5 caused significant (p > 0.05) elevation in doubling time for the MCF-7 breast cancer cell line." (PMID 31531019, 2019). "The results indicate that NAT1 may be an important regulator of cellular acetyl coenzyme A levels and strongly suggest that elevated NAT1 expression in breast cancers contribute to their anchorage-independent growth properties and ultimately metastatic potential." (PMID 31531019, 2019). "Indeed, NAT1 has been proposed as a prognostic marker for ER positive breast cancer." (PMID 29969986, 2018). "The study suggests that NAT1 may be a novel therapeutic target in a subset of breast cancers." (PMID 25627111, 2015). "Our findings, using mouse Nat2 to model human NAT1 function, indicate a novel aspect to the pattern of expression of mouse Nat2/human NAT1 during embryogenesis and will be important in understanding the role of the human NAT1 as a potential biomarker in breast cancer." (PMID 17896208, 2008). "The top five genes (NAT1, PPM1H, AREG, ACSS1, CXCL1) with the greatest differences in Z-scores were evaluated in the PIK3CA mutant breast cancer samples from TCGA." (PMID 38802751, 2024). "The data suggest that NAT1 expression is important for the proper functioning of mitochondria and the flux of glucose through the TCA/Krebs cycle in breast cancer cells." (PMID 37107601, 2023). "NAT1 expression levels also correlated with EMT status and metastatic behavior in breast cancer patients." (PMID 37350934, 2023). "We incubated breast cancer cells (MDA-MB-231 cells) and NAT1 Crispr KO cells (KO#2 and KO#5) with [U-13C]-glucose for 24 h." (PMID 37107601, 2023). "Moreover, the NAT1 mRNA level is associated with the overall survival of breast cancer patients and may be induced to identify non-responders to chemotherapy." (PMID 34867333, 2021). "CRISPR/Cas9 was used to make stable NAT1 KO human MDA-MB-231, MCF-7, and ZR-75-1 breast cancer cell lines." (PMID 31531019, 2019). "Other notable breast cancer related genes identified by super-delta include YBX1, KPNA2, SKP2, and NAT1." (PMID 29268715, 2017).
breast carcinoma (continued). "In the present study, we have used the invasive triple-negative human breast cancer cells MDA-MB-231, MDA-MB-436, and BT-549 to investigate the effects of shRNA-mediated NAT1 knockdown on cell morphology and on invasive capacity in vitro." (PMID 25627111, 2015). "Expression of NAT1, ERα, progesterone receptor (PgR) and HER2 was analyzed in 394 breast cancer samples by immunohistochemistry." (PMID 25528056, 2014). "We report that miR-1290 directly targets the NAT1 3′-UTR and that NAT1 protein expression is correlated with improved OS of breast cancer patients." (PMID 25528056, 2014). "Multivariable analyses using the LASSO revealed that expression of PGR, ESR1, NAT1, GABRP, TBC1D9, SLC39A6 and LRBA of the 32 gene candidates was collectively the most important predictors for both breast cancer mortality and recurrence." (PMID 23819905, 2013). "We are currently investigating the effect of NAT1 knock-down in MDA-MB-231, a highly metastatic breast cancer cell line, in nude mice." (PMID 21347396, 2011). "There were changes to the amino acid composition of NAT1 breast cancer cells following non-targeted metabolomics." (PMID 37107601, 2023). "Notably, a retrospective analysis of publicly available NAT1 and NAT2 gene expression data in established breast cancer cell lines, primary breast tumor tissues, and normal breast tissues showed a small positive correlation between the two genes." (PMID 35046826, 2021). "It is important to note that miR-6744-5p is not the first miRNA discovered to target NAT1 enzyme in breast cancer." (PMID 32296579, 2020). "Global, untargeted metabolomics was conducted via ultra performance liquid chromatography-tandem mass spectrometry (UPLC-MS/MS) on MDA-MB-231 breast cancer cell lines constructed with siRNA and CRISPR/Cas9 technologies to vary only in NAT1 N-acetylation activity." (PMID 32555504, 2020). "The ability of the NAT1 KO cell lines to form anchorage-independent colonies in soft agar was dramatically and consistently reduced in each of the MDA-MB-231, MCF-7, and ZR-75-1 breast cancer cell lines." (PMID 31531019, 2019). "A recent report demonstrated that congenic rats expressing high levels of rat N-acetyltransferase 2 (NAT2; ortholog to human NAT1) activity exhibited more mammary tumors, and this finding was independent of carcinogen metabolism." (PMID 31531019, 2019). "NAT1 expression showed a trimodal distribution in breast cancer samples (n = 1980) but not in tumor tissue from ovarian, prostate, cervical or colorectal cancers." (PMID 29969986, 2018). "The trimodal distribution supports multiple mechanisms for regulating NAT1 expression, which was specific to breast cancer and not seen in other cancers such as prostate, ovarian, cervical or colorectal." (PMID 29969986, 2018). "At present, the status of mouse Nat2, the equivalent of human NAT1, in a model of breast cancer has not been explored." (PMID 18280460, 2008). "The role of the human NAT1 enzyme in breast cancer has not been extensively explored, although it has previously been demonstrated that the anti-oestrogen compound tamoxifen is an inhibitor of human NAT1." (PMID 18280460, 2008). "Proteomic analysis and non-targeted metabolomics suggested that NAT1 KO may change the fate of glucose as it relates to the TCA/KREB cycle of the mitochondria of breast cancer cells." (PMID 37107601, 2023). "The absence of NAT1 in patient tumours may be a useful biomarker for selecting alternative treatments in a subset of breast cancer patients." (PMID 35918499, 2022). "Also, NAT1 reinforces EMT and metastasis by regulating CDH2 and β-catenin levels in breast cancer." (PMID 33435156, 2021). "Similarly, other studies also reported that breast cancer patients with NAT1-negative expression have a poor prognosis compared with those with NAT1-positive expression." (PMID 32793479, 2020).